EGFR (epidermal growth factor receptor)
Diseases named in the same sentence as EGFR in open-access papers (continued):
Sharing a sentence is not in itself a finding about the gene and the disease.
cyst (continued). "Although it was noted earlier in the overgrown cysts, the results described in this manuscript established a tight correlation between the EGFR-ERK activation in SCCs and synchronization of germline divisions in the cyst." (PMID 30045884, 2018). "Yet, the exact mechanism of how polarity and endocytosis regulate EGFR signaling levels under physiological conditions in the Drosophila testis and how EGFR is distributed to apical vs. basal cyst cell membranes is not yet established." (PMID 35563080, 2022). "Downregulation of EGFR in cyst cells affects synchronized spermatogonia TA-divisions and the localization of Armadillo on the cyst membrane, while somatic EGFR activation is not required to induce Bam expression." (PMID 33990549, 2021). "The role of EGF/EGFR appears to also depend on the postnatal developmental stage because in neonatal ARPKD mice, EGF treatment did not reduce cyst expansion and also caused early death." (PMID 34650051, 2021). "Inhibition of EGFR and VEGFR was shown to slow cyst growth in various PKD rodent models." (PMID 34650051, 2021). "Thus, inactivation of CG6015 in somatic cyst cells led to aberrant activation of ERK kinase in germ cells, along with differentiation defects, suggesting a possible role for CG6015 and EGFR signaling in germline differentiation in the stem cell niche." (PMID 33824283, 2021). "We found that Region 3 cysts were always present in germaria from control flies, but that 21% (n = 25/119) of the germaria with constitutively active EGFR signaling were elongated and completely lacked a Region 3 cyst." (PMID 25437306, 2014). "Immunohistochemical evaluation of Ki-67, AMH, aromatase, epidermal growth factor receptor, calretinin, and epithelial cadherin revealed no clear differentiation between large follicular structures of clinically unremarkable ovaries and cyst-like structures of neoplastic ovaries." (PMID 39409848, 2024). "We drove expression of constitutively active EGFR or Sprouty RNAi in adult hub cells (using E132-Gal4, Gal80ts) or Argos RNAi in adult cyst lineage cells (using C587-Gal4, Gal80ts), but we found no ectopic niches in any testes (n = 35, 285, or 291 testes, respectively)." (PMID 35468055, 2022). "Moreover, tesevatinib, an inhibitor of EGFR, HER2, c-SRC, and VEGFR, which reduced cyst growth in autosomal-recessive PKD (ARPKD) mice, was recently tested for efficacy and safety in a clinical phase-2 study in ADPKD patients (ClinicalTrials.gov Identifier: NCT03203642)." (PMID 34650051, 2021). "Interestingly, epidermal growth factor receptor (EGFR) ErbB-1 has previously been described for its involvement in cyst growth;37 however, inhibitors for EGFR were not identified as hits in our screen." (PMID 28644734, 2017). "Taken together, these results support the hypothesis that the EGFR pathway is actively inhibited in adult hub cells by at least two cell-autonomous inhibitors, Sprouty and PTEN, which maintain hub cell quiescence and prevent their conversion to cyst lineage cells." (PMID 35468055, 2022). "Thus, these authors suggested that Pkd1 mutation-induced upregulation of HDAC6 might slow the trafficking of EGFR from early endosomes to late endosomes along microtubules for degradation through deacetylation of α-tubulin, leading to phosphorylation of ERK1/2 to facilitate cyst formation." (PMID 30134806, 2018).
endothelial dysfunction (29 papers, 2013 to 2025). In vascular diseases, endothelial dysfunction is a systemic pathological state of the endothelium (the inner lining of blood vessels) and can be broadly defined as an imbalance between vasodilating and vasoconstricting substances produced by (or acting on) the endothelium. "Activation of EGFR has been implicated in blood pressure regulation, endothelial dysfunction, neointimal hyperplasia, atherogenesis, and cardiac remodelling." (PMID 39919333, 2025). "Activation of EGFR has been implicated in endothelial dysfunction, atherogenesis, and cardiac remodeling." (PMID 34515027, 2021). "We attributed this endothelial dysfunction to a reduced cEC metabolism caused by inhibition of the EGFR pathway." (PMID 34483880, 2021). "Activation of EGFR has been implicated in blood pressure regulation, endothelial dysfunction, neointimal hyperplasia, atherogenesis, and cardiac remodeling." (PMID 24132149, 2013). "Oscillatory shear stress downregulates the methyltransferase METTL3, destabilizing EGFR mRNA and thereby exacerbating endothelial dysfunction." (PMID 41462662, 2025). "Quercetin, for example, ameliorated endothelial dysfunction and inflammation in PE models by targeting epidermal growth factor receptor (EGFR) signaling." (PMID 40722994, 2025). "Mice with a deletion of the EGFR in endothelial cells develop a slight endothelial dysfunction, which is somewhat stronger in animals fed a high-fat diet." (PMID 37626737, 2023). "We showed that in mice, with deletion of the EGFR in VSMCs, the vascular responsiveness is altered towards different vasoactive substances, and that deletion of the EGFR in VSMCs protects at least in part from endothelial dysfunction." (PMID 37626737, 2023). "Adenovirus-mediated METTL3 overexpression significantly reduced EGFR activation and endothelial dysfunction in the presence of OS." (PMID 35001873, 2022). "Angiotensin II induces transactivation of EGFR through ROS generation, which can induce endothelial dysfunction and vascular inflammation." (PMID 35163238, 2022). "The activation of epidermal growth factor receptor (EGFR) is involved in blood pressure regulation and endothelial dysfunction." (PMID 35457136, 2022). "Previous studies have indicated that activation of EGFR is related to BP regulation, endothelial dysfunction, neointimal hyperplasia, atherogenesis, and cardiac remodeling." (PMID 34586716, 2021). "EGFR deletion protects the animals from HFD-induced endothelial dysfunction, creatininaemia and albuminuria." (PMID 32548701, 2020). "The activation of EGFR was implicated in CVD via the regulation of blood pressure, endothelial dysfunction, neointimal hyperplasia, atherogenesis, and cardiac remodeling." (PMID 33603661, 2020). "Moreover, METTL3 overexpression significantly reduced EGFR activation and endothelial dysfunction during oscillatory stress (OS)." (PMID 37273867, 2023). "Besides, endothelial dysfunction and vascular remodeling caused by IL-6, TGF-β, TNF-α, EGFR, and VEGFA are also some of the core features of CVD." (PMID 32454875, 2020). "Additionally, 20-HETE’s vasoconstrictive and diuretic effects have been linked to the PLC/PKC pathway, and its effects on vascular smooth muscle cell (VSMC) migration, endothelial dysfunction, and inflammation appear to involve the c-Src/EGFR pathway, which is commonly activated by GPCRs." (PMID 40362321, 2025). "Furthermore, the observed activation of Estrogen, VEGF, EGFR, and P13K pathways may remediate the reported endothelial dysfunction in Long COVID by enhancing microvascular support, nitric oxide-mediated vasodilation, and endothelial repair." (PMID 41332658, 2025). "Our study highlights that, although they are both arterial EC, female HAoEC and HCAEC are distinguishable with regard to the role of EGFR and its involvement in inflammation regulation, what may be relevant for vascular maintenance but also the pathogenesis of endothelial dysfunction." (PMID 38129563, 2023).
endothelial dysfunction (continued). "Our data revealed that downregulation of METTL3 and hypomethylation mediate OS-induced endothelial dysfunction and atherogenesis both in vivo and in vitro, indicating that the THBS1/EGFR axis is a key regulatory target of METTL3-dependent EC activation." (PMID 35001873, 2022). "A mechanistic analysis revealed that m6A could interact with the EGFR mRNA; m6A modification of the EGFR 3′UTR accelerated its mRNA degradation leading to endothelial dysfunction." (PMID 37273867, 2023).
inflammatory breast carcinoma (29 papers, 2007 to 2025). An advanced, invasive breast adenocarcinoma characterized by the presence of distinct changes in the overlying skin. "Inflammatory breast cancer (IBC) is characterized by NF‐κB activation, which causes endoplasmic reticulum (ER) downregulation, overexpression of EGFR and ErbB2, and hyperactivation of MAPK." (PMID 38077251, 2023). "This study also demonstrated that treatment of inflammatory breast cancer patients with an EGFR/HER2 dual-specificity kinase inhibitor significantly downregulated CTEN expression." (PMID 29137409, 2017). "It has been shown that lapatinib lacks efficacy in HER2-negative, EGFR-overexpressing inflammatory breast cancer." (PMID 26083256, 2015). "Epidermal growth factor receptor (EGFR) overexpression has been associated with prognostic and predictive value in inflammatory breast cancer (IBC)." (PMID 24886365, 2014). "This study takes into account the fact that inflammatory breast cancer commonly lacks ER/PR and more frequently harbors HER2 gene amplification (~40%), and EGFR overexpression (~30%), which is associated with a poor prognosis." (PMID 23731980, 2013). "About half of patients with TNBC and inflammatory breast cancer show overexpression of EGFR." (PMID 39802656, 2025). "Epidermal growth factor receptor (EGFR) serves as a key regulator in orchestrating the balance between immunosuppressive and immunostimulatory responses within the TME, particularly in inflammatory breast cancer." (PMID 41011568, 2025). "Inflammatory breast cancer (IBC) is often characterized by overexpression of epidermal growth factor receptors 1 and/or 2 (ErbB1, ErbB2) that activate downstream survival pathways phosphatidylinositol-3-kinase (PI3K)/protein kinase B (AKT) and MAPK." (PMID 32656079, 2020). "In inflammatory breast cancer (IBC), an immunosuppressive tumor microenvironment mediated by EGFR signaling may contribute to ICI resistance." (PMID 40560045, 2025). "Importantly, blocking EGFR signaling can induce remodeling of the tumor microenvironment (TME) towards an immunoresponsive phenotype in non-small cell lung cancer (NSCLC) and inflammatory breast cancer." (PMID 37545491, 2023). "Notably, while EGFR is overexpressed in around 50% TNBC and inflammatory breast cancers, we found that this gene, as well as its ligand AREG, was downregulated in the luminal A obese group." (PMID 29330624, 2018).
pneumonia (29 papers, 2012 to 2025). An acute, acute and chronic, or chronic inflammation focally or diffusely affecting the lung parenchyma, caused by an infection in one or both of the lungs (by bacteria, viruses, fungi, or mycoplasma.). "Compared to other EGFR-TKIs (e.g., osimertinib), gefitinib has lower selectivity for normal lung tissue, which may further increase the risk of pneumonia." (PMID 40071087, 2025). "Afatinib also exhibits higher risks of increased creatinine levels, pneumonia, and rash than those reported for other EGFR-TKIs." (PMID 40135231, 2025). "Management also diverges, High-dose glucocorticoids are the first-line treatment for ICI-related pneumonia, while EGFR-TKI-related ILD requires immediate discontinuation of the drug, with glucocorticoids used in combination if necessary." (PMID 40949116, 2025). "Therefore, we speculate that inhibition of EGFR signaling because of EGFR cleavage by NE inhibits alveolar epithelial regeneration and exacerbates lung injury caused by inflammatory cytokines released in pneumonia." (PMID 37119853, 2023). "Compared with the model group, isorhamnetin reduced the protein expressions of SYK, IL-6, MAPK14, MAPK8, TNF-α, AKT, p-Akt, PIK3CA, EGFR and IL-1β in lung tissues of pneumonia mice." (PMID 36506534, 2022). "Our previous research found a significant elevation in EGFR expression in the S/TB region in samples from patients with pneumonia." (PMID 32157214, 2020). "As S. aureus exotoxins are associated with severe diseases such as pneumonia, food poisoning, infective endocarditis, sepsis, atopic dermatitis and toxic shock syndrome (TSS), the interaction of exotoxins with the EGFR warrants further investigation." (PMID 27414801, 2016). "Nonetheless, the proposition that EGFR mutations constitute a risk factor for pneumonia remains unverified in the absence of direct clinical investigations." (PMID 40313247, 2025). "In addition, our results suggest that NE inhibitors promote the recovery of alveolar epithelium damaged by pneumonia by inhibiting EGFR degradation by NE." (PMID 37119853, 2023). "Although irradiation pneumonia did not cause any treatment-related deaths among participants in our study, the pulmonary toxicity associated with EGFR-TKIs is a cause for concern." (PMID 32563259, 2020). "There was an increased risk of developing EGFR-TKIs-related infections (Peto OR 1.34, 95%CI: 1.08-1.66, p = 0.008) and febrile neutropenia (Peto OR 2.48, 95%CI: 1.31-4.69, p = 0.005), but not for pneumonia (Peto OR 0.97, 95%CI: 0.73-1.29, p = 0.82)." (PMID 28107192, 2017). "In the subgroup analysis of the PACIFIC study, patients with EGFR mutations demonstrated an increased incidence of pneumonia relative to those with wild-type EGFR (11.0% versus 3.8%),the frequency of EGFR mutations in Asian patients is higher than that in non-Asian patients (38.4% vs. 14.1%)." (PMID 40313247, 2025). "EGFR TKI-induced intestinal lung disease and pneumonia were frequent fatal AEs in a study based on 53 cohorts of 9569 participants." (PMID 37542339, 2023). "Moreover, in EGFR/MET-driven tumor samples, there were also extensive areas of alveolar hyperplasia and pneumonia, with alveoli filled with macrophages and plasma cells surrounding the adenocarcinoma mass or within edematous areas in the tumor." (PMID 34298655, 2021). "pointed out that in patients with stage IV NSCLC undergoing EGFR-TKI and stereotactic radiotherapy, only 6.67% developed grade 2 pneumonia, with no observations of grade 3 or higher levels of pulmonary toxicity." (PMID 40071087, 2025). "The most likely clinical setting for the use of EGFR inhibitors is as an adjunct therapy to antibiotic use in treatment of mucosal infections such as mTSS, non-menstrual TSS or pneumonia through systemic administration." (PMID 27414801, 2016).
Cirrhosis (28 papers, 2010 to 2025). A chronic disorder of the liver in which liver tissue becomes scarred and is partially replaced by regenerative nodules and fibrotic tissue resulting in loss of liver function. "Several studies implicated the role of overexpression and activation of EGFR in the progression of cirrhosis." (PMID 32316635, 2020). "Dysregulation of signaling pathways (Wnt/β-catenin, Hippo/Yap, HGF/c-Met, Notch, and EGFR) contributes to impaired liver regeneration, fibrosis, cirrhosis, and other liver pathologies." (PMID 40260261, 2025). "Nevertheless, a clinical study of EGFR inhibition using erlotinib in patients with cirrhosis evaluating its ability to inhibit the progression to HCC is ongoing (ClinicalTrials.gov: NCT02273362)." (PMID 33806040, 2021). "Several studies have implicated the role of overexpression and activation of EGFR in the progression of cirrhosis and the elevation of the EGFR level as being common to patients with HCC." (PMID 32933027, 2020). "In experimental models, upregulated EGFR pathway members lead to fibrosis and cirrhosis, a common finding at liver transplantation after failed portoenterostomy for BA." (PMID 26379158, 2015). "Consistent with previously reported rat models of liver cirrhosis, EGFR expression was shown to decrease in this mouse study, whereas it has been reported to increase in human cirrhosis patients." (PMID 20618941, 2010). "EGFR and its activated signaling pathways play an important role in liver tissue regeneration after acute or chronic injuries, as well as in the development of cirrhosis and HCC, where EGFR is overexpressed." (PMID 38927059, 2024). "Studies have suggested that inhibiting EGFR may offer a promising therapeutic strategy for reducing fibrogenesis and preventing HCC in patients with high-risk cirrhosis." (PMID 38136237, 2023). "Other evidence supporting this hypothesis showed the association of the EGFR pathway with cirrhosis, fibrosis, and HCC, and the reversion of the expression of cirrhosis signature genes by the EGFR inhibitor erlotinib." (PMID 33540858, 2021). "Importantly, erlotinib, a specific EGFR inhibitor, reduces the expression of several EGFR ligands and also can reverse cirrhosis gene signature." (PMID 31216276, 2019). "Interestingly, genes associated with early cell cycle control (G1/S) and apoptosis in liver cells (TGFβ1, EGFR) were found downregulated in HCV-cirrhosis with HCC." (PMID 22792259, 2012). "It has been reported that the levels of TGF-α and EGFR mRNA increase at different stages of cirrhosis and HCC in the DENA rat model, and that blocking EGFR activity prevents development of HCC in DENA rats." (PMID 20704698, 2010). "There is little information available regarding the relative expression of EGFR and cyclin D1 on HCC that develops in livers with and without cirrhosis." (PMID 38414954, 2023).